EHMT1 (euchromatic histone lysine methyltransferase 1)
Diseases named in the same sentence as EHMT1 in open-access papers (continued):
Sharing a sentence is not in itself a finding about the gene and the disease.
hepatocellular carcinoma (1 paper, 2024). A malignant tumor that arises from hepatocytes. "MT1H plays tumor-suppressing roles by regulating the Wnt/β-catenin signaling pathway in hepatocellular carcinoma, and interacts with EHMT1, which promotes its methyltransferase activity in prostate malignancies." (PMID 38833013, 2024).
pancreatic cancer (1 paper, 2023). "In addition, we have shown that pharmacological inactivation of both EHMT1 and EHMT2 alters pancreatic cancer cell growth." (PMID 37782747, 2023).
psoriasis (1 paper, 2025). An autoimmune condition characterized by red, well-delineated plaques with silvery scales that are usually on the extensor surfaces and scalp. "This might be relevant in psoriasis since EHMT1 negatively regulates gene induction pathways mediated by NF-κB and type I interferon, and is involved in Treg cell differentiation." (PMID 40650108, 2025).
cancer (21 papers, 2014 to 2026). A tumor composed of atypical neoplastic, often pleomorphic cells that invade other tissues. "EHMT1/2 also have direct roles in DNA repair and are implicated in chemoresistance in several cancers." (PMID 31775874, 2019). "The EHMT1/2 inhibitor BIX-01294 is known to block the proliferation of cancer cell lines but has shown considerable toxicity problems in preclinical studies." (PMID 37120667, 2023). "Both EHMT1 and EHMT2 are aberrantly expressed in various cancers and associated with epithelial–mesenchymal transition (EMT), cancer stemness, and metastasis." (PMID 37663929, 2023). "The expression of Euchromatin histone lysine methyltransferase 1 and 2 (EHMT1/2) is deregulated in many cancers." (PMID 35740522, 2022). "Considering their unique physiological and pathophysiological functions, EHMT1/2 have emerged as cancer therapeutic targets and, as such, inhibitors targeting G9a and GLP evolved as a novel approach to cancer treatment." (PMID 35408693, 2022). "Although less widely analyzed, GLP/EHMT1 overexpression also correlates with poor prognosis in various cancers where its depletion led to positive outcomes." (PMID 35740522, 2022). "The expression of EHMT2 and EHMT1 is upregulated in various cancers and is correlated with poor clinical outcomes." (PMID 35740522, 2022). "Our reported findings further highlight the potential of EHMT1/2 inhibition to overcome targeted therapy resistance and prevent cancer progression." (PMID 31775874, 2019). "Silencing EHMT1 or EHMT2 in PC-3 cells also significantly decreased cancer cell migration." (PMID 37663929, 2023). "Therefore, alternative therapeutic approaches are needed to treat cancers with deregulated EHMT1/2 expression." (PMID 35740522, 2022). "Therefore, the results of the present study suggest that EHMT1 plays a critical role in the regulation of cancer cell apoptosis and the cell cycle by modulating CDKN1A expression." (PMID 34214254, 2021). "Evidence of an association with breast cancer has been found for variants of EHMT1, although the physiological functions of this gene in cancer cells have not been elucidated." (PMID 34214254, 2021). "Further functional analyses of EHMT1 in the context of human tumorigenesis may aid in the development of novel therapeutic strategies for cancer." (PMID 34214254, 2021). "Histone H3 lysine 9 methylation (H3K9me), which is written by the Euchromatic Histone Lysine Methyltransferases EHMT1 and EHMT2 and read by the heterochromatin protein 1 (HP1) chromobox (CBX) protein family, is dysregulated in many types of cancers." (PMID 37782747, 2023). "Many cancers show aberrant silencing of gene expression and overexpression of histone methyltransferases, including EZH2 and EHMT1/2." (PMID 26300989, 2015). "EHMT1 and EHMT2, homologous SET domain–containing KMTs, have emerged as regulators of cancer metabolism, promoting glycolysis and sustaining serine-glycine biosynthesis in cancer cells." (PMID 39062577, 2024). "In contrast, EHMT1/2 inhibitors are still underdeveloped, and none of these inhibitors have been tested in clinical trials for cancer." (PMID 37663929, 2023). "These modifications also change the functions of EHMT1 and EZH2 from transcription corepressors to possible coactivators, highlighting the significant role of posttranslational modifications of histone-modifying proteins in mediating epigenetic reprogramming in cancer." (PMID 37663929, 2023). "To further elucidate the enzymatic role of G9a in cancer, we describe herein the biological activities of a novel peptide-competitive histone methyltransferase inhibitor, A-366, that selectively inhibits G9a and the closely related GLP (EHMT1), but not other histone methyltransferases." (PMID 26147105, 2015).
neurodevelopmental disorder (20 papers, 2014 to 2026). A behavioral and cognitive disorder with onset during the developmental period that involves impaired or aberrant development of intellectual, motor, or social functions. "The CNVs involved known disease genes (EHMT1, MBD5 and SCN1A) and imbalances in genomic regions associated with neurodevelopmental disorders (16p11.2, 16p13.11 and 2q13)." (PMID 27113213, 2016). "On the other hand, balanced chromosomal abnormalities seen in ASD and related neurodevelopmental disorders are reported to disrupt the EHMT1 gene." (PMID 25400900, 2014).
tumor (12 papers, 2015 to 2024). "Although EHMT1/2 are viewed mainly as oncogenes, a few studies have shown that they can have tumor-suppressive functions." (PMID 35740522, 2022). "According to the obtained results, EHMT1 was significantly related to apoptosis and the cell cycle process and had an important impact on regulating the apoptosis and cell cycle of tumor cells by regulating the expression of CDKN1A." (PMID 36092868, 2022). "We have shown that combined inhibition of EHMT1/2 and EZH2 increases growth inhibition in tumour cells over inhibition of only EHMT1/2 or EZH2 and results in re-expression of silenced genes." (PMID 26300989, 2015). "In the TCGA dataset, EHMT1 and EHMT2 are not differentially expressed in GATA3-ext tumours and do not show a segmentation pattern." (PMID 27588951, 2016).
psychiatric disorder (7 papers, 2014 to 2025). A disorder characterized by behavioral and/or psychological abnormalities, often accompanied by physical symptoms. "EHMT1 is a risk gene associated with a number ofneurodevelopmental and psychiatric disorders, thus itwas important for this work to focus not only on translational phenotypesbut those that overlap traditional diagnostic boundaries." (PMID 32954001, 2020). "The results are indicative of a vulnerability to develop severe psychiatric disorders that carriers of an EHMT1 mosaic mutation possess." (PMID 29416845, 2018).
infection (3 papers, 2019 to 2025). The state of being infected such as from the introduction of a foreign agent such as serum, vaccine, antigenic substance or organism. "Overall, our results led to the identification of nucleo-cytoplasmic isoforms of EHMT1 that associate with SeV IBs upon infection." (PMID 39509467, 2024). "Collectively, these results reveal that distinct nucleo-cytoplasmic forms of EHMT1 associate with the viral nucleoprotein in IBs formed either upon infection or co-transfection." (PMID 39509467, 2024). "Transfection of mCh_N resulted in diffused cytoplasmic expression of N and EHMT1 but upon infection, cytoplasmic condensates of mCh_N were observed, marking the IBs." (PMID 39509467, 2024). "Overall, we found that cytoplasmic EHMT1 and EHMT2 associate with each other as well as the viral nucleoprotein upon infection." (PMID 39509467, 2024). "The results showed that shEHMT1 infection [HG(4 d)+LG(4 d)/shEHMT1] decreased EHMT1 mRNA expression to 28% compared to the LG(8 d) group, indicating a successful knockdown by the shEHMT1 lentivirus." (PMID 31685635, 2019). "Quantification of the levels of EHMT1 in the nuclear and cytoplasmic fractions of the infected cells by normalising with the respective uninfected lanes revealed a minute but significant reduction in EHMT1 in both the nuclear as well as the cytoplasmic compartments upon infection." (PMID 39509467, 2024). "Thus, an incremental recruitment of EHMT1 to SeV IBs over the time course of infection is reflected on its methyltransferase activity on the SeV nucleoprotein and formation of large IBs." (PMID 39509467, 2024). "Considering that viral IBs recruit host proteins, we hypothesised that SeV could be inducing nuclear to cytoplasmic shuttling of EHMT1 upon infection." (PMID 39509467, 2024). "Similarly, piRFP_P and EHMT1 when transfected independently, was diffused in the cytoplasm but condensed into SeV IBs upon infection, where EHMT1 was found to localize." (PMID 39509467, 2024). "During infection by cytoplasmic RNA viruses like Influenza, Sendai, and VSV, IFNβ expression is increased by releasing the repression laid by EHMT1 to inhibit viral replication." (PMID 39509467, 2024). "Thus, to assess if the Interferon pathway regulated by the nuclear EHMT1 has any influence on the cytoplasmic viral processes, we profiled the expression of IFN and related genes upon infection." (PMID 39509467, 2024). "We then tested the impact of EHMT’s inhibition on these inert IBs and found that treatment with BIX/UNC did not have an impact on these IBs, indicating that EHMT1 probably exerts its effect only on large IBs formed upon infection." (PMID 39509467, 2024). "Since inhibition/depletion of EHMT1 led to the formation of smaller IBs, we examined if a relationship existed between the size of IBs and the inclusion of EHMT1N/C over the time course of infection." (PMID 39509467, 2024). "Having established a distinction between IBs formed upon infection and independent of infection (mini replicon and N+P co-transfection), we wanted to examine whether EHMT1 regulates the formation of IBs in the co-transfection system." (PMID 39509467, 2024). "We next examined if N and P are responsible and sufficient for the recruitment of EHMT1 in the absence of infection, towards which, we performed ICC against EHMT1 in co-transfected cells." (PMID 39509467, 2024).
EHMT1 also shares sentences with these, for which no sentence is quoted: developmental delay (9 papers); Kleefstra syndrome 1 (6); genetic disorder (4); Rett syndrome (4); Coffin-Siris syndrome (3); epilepsy (3); Kabuki syndrome (3); Angelman syndrome (2); dyslipidemia (2); fragile X syndrome (2); Weaver syndrome (2); Wiedemann-Steiner syndrome (2); adenocarcinoma (1); Alagille syndrome (1); arachnoid cyst (1); Autosomal Dominant Mental Retardation 1 (1); behavioral disorders (1); bladder cancer (1); brain tumor (1); cardiac arrhythmias (1); Christianson syndrome (1); chronic myeloid leukemia (1); ciliopathy (1); colon cancers (1); Cornelia de Lange syndrome (1); developmental arrest (1); esophageal cancer (1); Floating-Harbor syndrome (1); Glucose intolerance (1); Hartsfield syndrome (1).
A further 26 diseases each share a sentence with EHMT1 in 1 paper.